CD226 (CD226 molecule)
Diseases named in the same sentence as CD226 in open-access papers (continued):
Sharing a sentence is not in itself a finding about the gene and the disease.
Autoimmunity (17 papers, 2012 to 2025). The occurrence of an immune reaction against the organism's own cells or tissues. "On the other hand, TIGIT competes for CD155 binding with CD226, a receptor associated with the hyperinflammation of autoimmune disorders, suggesting the existence of a host-driven “cytokine storms” axis opposed to the virally induced immune suppressant, TIGIT." (PMID 32655579, 2020). "Moreover, loss of the inhibitory molecule TIGIT which competing for the same ligand with CD226, resulted in hyperproliferative T cell responses and increased susceptibility to autoimmunity." (PMID 26942885, 2016). "The dysregulation of CD226 signaling—through genetic polymorphisms, altered expression, or imbalanced ligand interactions—disrupts immune homeostasis and is mechanistically linked to aberrant inflammation, autoimmunity, and impaired pathogen/tumor surveillance." (PMID 40723878, 2025). "On one hand, our data related to CD226 being highly expressed on effector T cells supports additional studies targeting this pathway in vivo to block destructive autoimmunity." (PMID 35693814, 2022). "Recent studies also demonstrated the importance of the 3′-UTR SNP rs727088 in the regulation of DNAM-1/CD226 transcription in T and NKT cells and its association with autoimmunity." (PMID 23476104, 2013). "Studies in murine models demonstrate that CD226 deficiency in Tregs alleviates insulitis and delays diabetes onset in non-obese diabetic (NOD) mice, suggesting a suppressive function for CD226 in Treg-mediated tolerance during autoimmunity." (PMID 40723878, 2025). "Furthermore, new therapeutic approaches based on anti-CD226 mAb treatment have already been tested in autoimmunity animal models, and CD226 has been recently implied in novel T cell activation pathways and NK-driven tissue injury in SLE patients." (PMID 22531499, 2012). "Therefore, CD226 may augment peripheral CD8+ T cell activation within the context of organ-specific autoimmunity." (PMID 33013915, 2020). "Notably, IL-10 and DNAX accessory molecule-1 (DNAM-1, also known as CD226) secreted by NK cells can also inhibit T cell response via deletion of CTL, thus preventing the phenomenon of autoimmunity." (PMID 36231109, 2022). "Because CD4+ T cells play a central role in autoimmunity, and CD226 promotes self-reactive CD4+ T cell activation in the autoimmune response, we considered whether CD226 functions by altering the balance of CD4+ T cell subsets involved in the pathogenesis of EAE." (PMID 32983109, 2020).
rheumatoid arthritis (16 papers, 2011 to 2025). A chronic, systemic autoimmune disorder characterized by inflammation in the synovial membranes and articular surfaces. "Genetic studies have pointed out that CD226 variants, encoding DNAM-1, could be associated with susceptibility to rheumatoid arthritis." (PMID 25685070, 2015). "1-Lee YH, Bae SC, Song GG: Association between the CTLA-4, CD226, FAS polymorphisms and rheumatoid arthritis susceptibility: a meta-analysis." (PMID 27454254, 2016). "Moreover, CD226 has been identified as an autoimmune susceptibility gene, and its allelic variants are linked to the development of multiple sclerosis (MS), systemic lupus erythaematosus (SLE), rheumatoid arthritis (RA), and juvenile idiopathic arthritis (JIA)." (PMID 32983109, 2020). "In addition to contributing to decreased regulatory function, CD226 has been identified to contain a potential gain-of-function risk variant contributing to a propensity for multiple autoimmune diseases including T1D, SLE, rheumatoid arthritis (RA), and multiple sclerosis (MS)." (PMID 35693814, 2022).
acute myeloid leukemia (15 papers, 2015 to 2025). Acute myeloid leukemia (AML) is a group of neoplasms arising from precursor cells committed to the myeloid cell-line differentiation. "Acute myeloid leukemia blasts reduce CD226 expression on NK cells, suggesting a mechanism of tumor escape by impairing the cytotoxicity of NK cells." (PMID 40723878, 2025). "Acute myeloid leukemia (AML) cells have developed mechanisms to escape NK cell cytotoxicity, including inducing downregulation of CD226 on NK cells." (PMID 40624674, 2025).
leukemia (15 papers, 2013 to 2026). A malignant (clonal) hematologic disorder, involving hematopoietic stem cells and characterized by the presence of primitive or atypical myeloid or lymphoid cells in the bone marrow and the blood. "In an AML xenograft model, mice treated with CD226 overexpression iPSC-NK cells exhibited significantly reduced leukemia burden, prolonged survival, decreased systemic inflammation compared to those treated with Control iPSC-NK cells." (PMID 40624674, 2025). "Primed CD226-deficient CD8 + T cells elicited a reduced cytotoxic effect on PVR-expressing mouse tumor cell lines, whereas CD226 deficiency did not affect the expansion of CD8 + T cells upon co-culture with mouse leukemia RMA cells that did not express PVR66." (PMID 39349829, 2024). "Additionally, NK cell-mediated lysis of leukemias was dependent on CD226." (PMID 34884723, 2021).
viral infection (15 papers, 2013 to 2025). "All these highlight the important role of TIGIT/CD226 axis in viral infections and suggest a potential new avenue for the development of therapeutic strategies toward a functional cure." (PMID 32850777, 2020). "In response to viral infection, CD226 KO mice showed delayed lymphocytic choriomeningitis virus (LCMV) clearance, with reduced IFNγ and TNFα production by virus-specific CD8+ T cells." (PMID 33013915, 2020). "CD226 on monocytes/ macrophages interacted with CD155 on NK cells to control virus infection." (PMID 34823548, 2021). "In particular, the DNAM-1 (CD226) receptor is known to be essential for NK cell–dependent antitumor immunity, and its role in immune responses to viral infections is emerging." (PMID 31366013, 2019). "Expression levels of the inhibitory receptor, T cell immunoglobulin and ITIM domain (TIGIT), the co-stimulatory receptor CD226 and their ligand PVR are altered in viral infections and cancer." (PMID 28084312, 2017).
hepatocellular carcinoma (13 papers, 2017 to 2025). A malignant tumor that arises from hepatocytes. "miR892a modulates the FBLN1, MYH7B and MST1R genes and is known to promote proliferation and invasion of hepatocellular carcinoma cells via targeting CD226." (PMID 34357026, 2021). "NK cells require CD226 for recognition of HCV-infected hepatoma cells and HCMV-infected myeloid DCs." (PMID 32850777, 2020). "Similarly, CD155-expressing hepatocellular carcinoma cells induce CD226 downregulation, impairing CD226-mediated cytotoxicity in both tumor-infiltrating and circulating NK cells, which contributes to the tumor evasion of innate immune surveillance." (PMID 40723878, 2025). "Activating receptors of NK cells, such as NKG2D, CD226, and NKp30, are downregulated on NK cells and correlate inversely with the progression and metastasis of melanoma, colorectal carcinoma, hepatocellular carcinoma (HCC), breast cancer, prostate cancer, gastric cancer, and others." (PMID 32714324, 2020).
systemic lupus erythematosus (13 papers, 2014 to 2025). An autoimmune multi-organ disease typically associated with vasculopathy and autoantibody production. "CD226, an activating receptor expressed on the surface of natural killer (NK) cells and T cells, is also seen on B cells and CD226 polymorphism is associated with systemic lupus erythematosus (SLE)." (PMID 34367178, 2021). "Additionally, the CD226 rs763361 polymorphism is linked to elevated risk of systemic lupus erythematosus, particularly in Chinese Han populations." (PMID 40723878, 2025). "However, CD226+ NK cells are deficient in active systemic lupus erythematosus, potentially due to activation-induced cell death." (PMID 40723878, 2025). "Although CD226 polymorphism is known to be involved in systemic lupus erythematosus (SLE), the involvement of soluble CD226 (sCD226) in SLE is still unknown." (PMID 34373559, 2021). "Research from other laboratories has also highlighted the pathogenic role of CD226+ B cells in systemic lupus erythematosus (SLE)." (PMID 40957221, 2025). "CD226 was previously reported to be associated with multiple autoimmune diseases such as systemic lupus erythematosus (SLE)." (PMID 38659056, 2024). "CD226+ B cells, particularly switched-memory subsets, are increased in systemic lupus erythematosus patients and correlated with higher disease activity." (PMID 40723878, 2025). "Elevated serum soluble CD226 levels are observed in active systemic lupus erythematosus and correlate with disease activity indices and anti-dsDNA antibody titers, positioning soluble CD226 as a biomarker to monitor disease flares." (PMID 40723878, 2025). "Moreover, basal percentages of CD226+ B cells and CD226+ SM B cells were low in patients who were in Lupus Low Disease Activity State after 12 months." (PMID 34367178, 2021). "On the contrary, CD226+ NK cells infiltrate the kidneys of predisease lupus mice and these infiltrating NK cells display an activated phenotype and a marked ability to produce cytokines and cytotoxic granules, suggesting they may mediate tissue injury." (PMID 34012432, 2021). "We then confirmed that these genes, such as IL32, CD226, CDKN1A, and PTPRN2 were similarly hypomethylated in lupus patients of African-American compared to European-American descent." (PMID 26609326, 2015).
pancreatic cancer (12 papers, 2013 to 2025). "In pancreatic cancer, high CD226 expression on CD8+ T cells is associated with response to PD1 and TIGIT blockade." (PMID 36717657, 2023). "Supporting a role for CD226 and CD96 in the context of tumour evasion, a study of patients with pancreatic cancer demonstrated that CD226+CD96+ NK cells are deficient in patients versus healthy controls, while TIGIT was not altered." (PMID 30908480, 2019). "There seems to be a dysregulation of the TIGIT/CD96/CD226/CD155 pathway involving NK cells in pancreatic cancer patients, warranting further in vitro and in vivo evaluation." (PMID 32117298, 2020). "However, TIGIT expression was found to be similar between pancreatic cancer patients and healthy controls, while CD226 and CD96 were downregulated." (PMID 32117298, 2020). "Additionally, recent studies demonstrated that the CD155/TIGIT axis is a key driver of immune evasion in pancreas cancer, and that both PD-1 and TIGIT signaling impairs CD226 co-stimulation which is required for restoring antitumor immunity." (PMID 36569934, 2022).
COVID-19 (11 papers, 2020 to 2025). A disease caused by infection with severe acute respiratory syndrome coronavirus 2. "This study highlights the role of PD-1/PD-L1 and the TIGIT/CD226/CD155/CD112 pathways in COVID-19 patients." (PMID 39764446, 2024). "More importantly, single-cell sequencing revealed that COVID-19 patients with renal failure exhibited lower metabolic activity in lung epithelial and B cells, with reduced ligand–receptor interactions, especially CD226 and ICAM, suggesting a compromised immune response." (PMID 39202702, 2024). "Indeed, a significantly higher frequency of CD226 was detectable on bulk CD8+ T cells in both COVID-19 and malaria compared to healthy individuals." (PMID 32983106, 2020). "Considering the significant alterations of NKeff cells subset in COVID-19 patients, a detailed assessment of the immunophenotype of NKeff cells subset was conducted, focusing on markers including CD69, KIR, CD52, CD226, NKG2D, and CD62L using flow cytometry." (PMID 40471558, 2025). "We noted a considerable decrease in the NKeff cells subset among COVID-19 patients, marked by heightened KIR expression along with reduced levels of NKG2D and CD226." (PMID 40471558, 2025). "Our analysis revealed a trend towards elevated expression of CD69, KIR, and CD52, alongside diminished expression of CD226, NKG2D, and CD62L in patients who contracted COVID-19, when contrasted with those with T2D or control subjects." (PMID 40471558, 2025). "Overall, we observed a strong activation of T cells in COVID-19 and malaria with an increased expression of both early (CD69+) and late (HLA-DR+CD38+) activation markers as well as the co-stimulatory receptor CD226." (PMID 32983106, 2020). "In addition to the analysis of the traditional activation markers, we also looked at the expression of the co-stimulatory receptor CD226 on CD8+ and CD4+ T cells in COVID-19 and malaria patients compared to healthy individuals." (PMID 32983106, 2020). "Furthermore, when COVID-19 patients were compared with patients with T2D or control subjects, a trend was noted toward increased expression of CD69, KIR, and CD52 and decreased expression of CD226, NKG2D, and CD62L." (PMID 40471558, 2025). "An intriguing observation is that in COVID-19 patients with T2D, the NKeff cells subset exhibits an increased presence of inhibitory receptors, specifically KIRs, and a reduced presence of activating receptors DNAM1 (CD226) and NKG2D, as opposed to patients with only COVID-19 or T2D." (PMID 40471558, 2025).
diabetes (11 papers, 2011 to 2025). "Functional studies in NOD mice models have shown that CD226 deficiency or blockade delays insulitis onset and reduces diabetes incidence by inhibiting effector T cell activation and enhancing Treg function." (PMID 40723878, 2025). "SNPs in CD226 are associated with T1D, and deletion of this gene protects against diabetes in the NOD mouse." (PMID 37164005, 2023). "Our previous study showed that CD226 on endothelial cells contributes to hyperglycemia in type 2 diabetes mellitus by suppressing glucose uptake in endothelial cells." (PMID 34823548, 2021). "CD226 blockade delays the onset of insulitis and mitigates the severity of hyperglycemia in both streptozotocin-induced and cyclophosphamide-induced murine diabetes models." (PMID 40723878, 2025). "Importantly, we observed that CD226 KO showed significantly reduced diabetes incidence, with 52% of KO females (N = 11/21, p = 0.021) and 13% of KO males (N = 2/16, p = 0.004) developing disease." (PMID 33013915, 2020). "In a Treg Cd226 conditional knockout model, female NOD mice also displayed decreased insulitis and diabetes incidence, supporting the notion that CD226 is involved in Treg stability." (PMID 41480350, 2025). "However, blocking PD1 signaling increased CD226 and TIGIT co-expressing cells, and TIGIT inhibition led to rapid diabetes in NOD mice." (PMID 38533515, 2024).
glioma (10 papers, 2019 to 2025). A benign or malignant brain and spinal cord tumor that arises from glial cells (astrocytes, oligodendrocytes, ependymal cells). "Subsequent analysis in TCGA dataset indicated that CD155 was positive associated with CD96, CD226, and Nectin4 in glioma and GBM samples." (PMID 31377744, 2019). "CD155 showed strong positive concordance with CD96, CD226, and Nectin4 in all gliomas and GBM samples from Rembrandt dataset." (PMID 31377744, 2019). "Our study showed RS was interconnected with CD16, CD226, CD96 and CD112, which could activate NK cells to kill glioma cells to achieve prolonged survival." (PMID 35236310, 2022).
lung carcinoma (10 papers, 2019 to 2026). "Importantly, circulating miR-150-5p were increased in the serum of patients with lung cancer, and these increased serum levels were positively associated with the ability to decrease the expression of CD226 in NK cells." (PMID 34944871, 2021). "To establish whether there is an association between CD226 expression on NK cells and overall survival in patients with lung cancer, we analyzed public data from The Cancer Genome Atlas (TCGA)." (PMID 34944871, 2021). "Here, we show that TIGIT and CD226 are infrequently co-expressed on both peripheral blood and particularly so on tumour infiltrating lymphocytes in renal and lung cancer." (PMID 37596248, 2023). "Treatment of NK92 cells with EVs isolated from the serum of lung cancer patients, decreased their expression of CD226, and this effect was significantly, yet weakly, correlated with the level of miR-150-5p in the serum EVs (R = −0.26, p = 0.003)." (PMID 34944871, 2021). "We revealed CD226 downregulation and functional repression of NK cells after hypoxic lung cancer priming and we then investigated their interaction with extracellular vesicles (EVs) and miR-150-5p." (PMID 34944871, 2021). "The upregulated expression of NKG2A and downregulated level of CD226 were observed in the lung cancer group compared with the control group in a previous study." (PMID 34944871, 2021). "It has been reported that CD226 was decreased in peripheral blood NK cells from patients with gastric or lung cancer." (PMID 34944871, 2021). "CD226 expression is not only associated with PD-1/PD-L1 in CRC, but also in triple-negative breast cancer, lung adenocarcinoma and lung carcinoma suggested by TCGA." (PMID 34417435, 2021). "We also found that NK cells from lung cancer patients had lower expression of CD226 on their surface and exhibited a pro-inflammatory, pro-angiogenic and tumorigenesis phenotype." (PMID 34944871, 2021). "We also found that NK cells from lung cancer patients had lower expression of CD226 on their surface and exhibited a pro-inflammatory, pro-angiogenic and tumorigenesis phenotype by expressing VEGF, CXCL1, CXCL8, S100A8 and MMPs." (PMID 34944871, 2021). "Flow cytometry showed that hypoxic lung cancer cell-derived EVs decreased the expression of CD226 on NK cells, suggesting that hypoxic CL1-5-derived EVs downregulated the activating receptor CD226 and thereby impair the cytotoxicity of NK cells." (PMID 34944871, 2021). "We determined the functional profiles of NK cells in a hypoxic tumor microenvironment (TME) of lung cancer, revealing CD226 downregulation and functional repression of NK cells after treated with hypoxic lung cancer-derived extracellular vesicles (EVs) containing miR-150-5p." (PMID 34944871, 2021). "The manipulation of NK function via CD226 expression may be a feasible strategy for the treatment of lung cancer." (PMID 34944871, 2021). "In this study we demonstrate that T and NK cells within both the blood and tumours of renal and lung cancer patients seldom co-express TIGIT and CD226, suggesting that within certain tumours TIGIT acts predominantly independently of CD226 cis interactions." (PMID 37596248, 2023). "However, excessive activation led to decreased CD226 expression, altered NK cell activity, and reduced IFN-g secretion, ultimately increasing the metastatic properties of lung cancer cells." (PMID 41596586, 2026).
multiple sclerosis (10 papers, 2015 to 2025). A progressive autoimmune disorder affecting the central nervous system resulting in demyelination. "CD226 rs763361C > T is associated with multiple autoimmune diseases, including multiple sclerosis and rheumatoid arthritis." (PMID 33469055, 2021). "The rs763361 nonsynonymous variant in the CD226 gene, which results in a glycine-to-serine substitution at position 307 of the CD226 protein, has been implicated as a risk factor of various immune-mediated diseases, including multiple sclerosis (MS)." (PMID 39231385, 2024). "An increase in soluble CD226 levels has been detected in multiple sclerosis and neuromyelitis optica patients, correlating with neuroinflammation and disease progression." (PMID 40723878, 2025). "The CD226 Gly307Ser (rs763361) polymorphism is correlated with a higher risk of neuromyelitis optica in Southern Han Chinese, but not with multiple sclerosis." (PMID 40723878, 2025). "The CD226-307Ser risk variant enhances interferon-γ (IFN-γ) signaling in CD8+ T cells via increased ERK1/2 and signal transducer and activator of transcription (STAT) 4 phosphorylation, contributing to chronic inflammation in conditions like multiple sclerosis." (PMID 40723878, 2025).